PCDHA6 (protocadherin alpha 6)
Description:
Potential calcium-dependent cell-adhesion protein. May be involved in the establishment and maintenance of specific neuronal connections in the brain.
Synonyms: CNRS2; CNR2; CRNR2; PCDH-ALPHA6; CNRN2
Tractability: Antibody: UniProt places it where antibodies can reach, with high confidence; its Gene Ontology location is reachable by antibodies, with high confidence; UniProt predicts a signal peptide or a membrane-spanning region.
Gene: Protein-coding gene on chromosome 5 (140,827,958 to 141,012,347, forward strand). Ensembl gene ENSG00000081842.
Subcellular location: Cell membrane (Isoform 1); Secreted (Isoform 2)
Subcellular location (Human Protein Atlas): Vesicles; Predicted to be secreted
Gene Ontology:
Molecular function: cell adhesion molecule binding; calcium ion binding
Biological process: cell adhesion; nervous system development; homophilic cell-cell adhesion
Cellular component: plasma membrane; extracellular region; membrane
Genetic constraint (gnomAD): Loss-of-function variants: 53 observed, 61.15 expected, observed/expected ratio (o/e) 0.87, 90% interval 0.69 to 1.09. The upper end of that interval is the gene's LOEUF score, 1.09, which puts it in group 4 of 6, group 1 being the genes least tolerant of losing a copy. Missense variants: 1,315 observed, 1,295.6 expected, observed/expected ratio (o/e) 1.01, 90% interval 0.97 to 1.06. Synonymous variants: 649 observed, 576.14 expected, observed/expected ratio (o/e) 1.13, 90% interval 1.05 to 1.2.
Homologues: Orthologues: mouse Pcdha6 (85% identical). Paralogues in human: PCDHA8 (91% identical), PCDHA3 (83% identical), PCDHA10 (81% identical), PCDHA4 (81% identical), PCDHA5 (81% identical), PCDHA11 (81% identical), PCDHA7 (81% identical), PCDHA1 (81% identical), PCDHA13 (81% identical), PCDHA2 (81% identical), PCDHA9 (80% identical), PCDHA12 (80% identical), and 49 more.
Diseases named in the same sentence as PCDHA6 in open-access papers:
PCDHA6 is named in the same sentence as 6 diseases in open-access papers, as found by Europe PMC text mining. Sharing a sentence is not in itself a finding about the gene and the disease. The quoted sentences say what the papers report.
cancer (3 papers, 2017 to 2025). A tumor composed of atypical neoplastic, often pleomorphic cells that invade other tissues. "Ingenuity pathway analysis revealed that differentially methylated CpG sites were annotated to genes involved in ‘cell cycling’ (e.g. NDRG1, NEDD1, and MAD1L1), ‘inflammatory diseases’ (e.g. PRTN3), and ‘cancer’ (PCDHA6, MUC4, and ATP2C2)." (PMID 28754985, 2017). "The effectors of migration and apoptosis in other cancers and developing tissues were differentially expressed: LCP1 and CXCL5 were upregulated, while PROSER2 and PCDHA6 were downregulated." (PMID 40323130, 2025).
PCDHA6 also shares sentences with these, for which no sentence is quoted: bipolar disorder (1 paper); mental illness (1); neurodegenerative disease (1); ovarian epithelial cancer (1); Stroke (1).